AFP (alpha fetoprotein)
Diseases named in the same sentence as AFP in open-access papers (continued):
Sharing a sentence is not in itself a finding about the gene and the disease.
diabetes (continued). "A 60-year-old man with a history of diabetes mellitus underwent medical check-up at a primary care clinic, where he was found to have esophageal varices and an elevated alpha-fetoprotein (AFP) level." (PMID 40429964, 2025). "Multivariate analysis highlighted the significance of parameters such as albumin, total bilirubin, AFP, the presence of diabetes mellitus, and a tumor size < 5 cm in the PNS-positive group compared to the PNS-negative group." (PMID 38674198, 2024). "The strength of the association between abundance of the 150 metabolites or AFP with risk for HCC was further determined by logistic regression analysis, adjusting for age, gender and diabetes." (PMID 39139459, 2024). "BMI, hypertension, preoperative diabetes mellitus, HBsAg positivity, AFP, ALB, GGT, FPG, TG, HDL-C, tumor size, number of tumors, TG/HDL-c, and TyG-BMI differed significantly between the high and low TyG groups." (PMID 39537878, 2024). "Consistent significant risk factors were age, current smoking, higher alpha-fetoprotein (AFP), diabetes, and cerebrovascular disease." (PMID 36820368, 2023). "Upon reviewing the available literature, little information was found about the potential effect of MT on the regulation of hepatic alpha-fetoprotein expression and pancreatic beta cells in diabetes." (PMID 37655263, 2023). "In the univariate analysis, age ≥ 71 years, diabetes, platelet count < 12.0 × 104/μL, AFP ≥ 4.2 ng/mL, FIB4 index ≥ 2.73, and LSM ≥ 8.4 kPa were identified as factors significantly associated with HCC after SVR." (PMID 35087141, 2022). "First, pre-treatment univariate analysis revealed that age ≥ 71 years, diabetes, platelet count < 13.2 × 104/μL, albumin < 3.9 g/dL, AFP ≥ 6.2 ng/mL, FIB 4 index ≥ 3.25, and LSM ≥ 9.2 kPa were significant contributors of HCC occurrence." (PMID 35087141, 2022). "Multivariate Cox regression analysis indicated that diabetes, AFP, APRI, SIRI, MVI, number of tumours, tumour diameter and PVTT were independent risk factors for 1-year RFS; female and ALT were independent protective factors for 1-year RFS." (PMID 35255845, 2022). "We demonstrated that diabetes mellitus, AFP 12M, FIB-4 12M, and changes in FIB-4 values were independent predictors of HCC for the entire cohort." (PMID 32392752, 2020). "FZHY group exhibited a higher rate of diabetes, hypertension, total bilirubin, gamma-glutamyl transferase, white blood cell count, prothrombin activity, and alpha-fetoprotein than the control group." (PMID 33178324, 2020). "The univariate logistic regression analysis revealed that the antiviral therapy, diabetes, ascites, LY%, HGB, AST, GGT, CHE, AFP, and CTP class were factors associated with rebleeding." (PMID 31226942, 2019). "We observed that steatosis on ultrasonography was associated with factors representative of inflammation (histologic grade on biopsy and ALT) and fibrosis (histologic stage on biopsy and alpha-fetoprotein levels) as well as diabetes mellitus." (PMID 15829009, 2005). "The comparison of baseline and clinical characteristics between patients with versus without steatosis on ultrasound indicated significant differences in ALT and AFP, a history of diabetes mellitus, and advanced histologic stage and grade." (PMID 15829009, 2005). "In addition, it is well known that various other factors can affect the survival of HCC patients, such as geographical factors, serum alpha-fetoprotein (AFP) level, variant estrogen receptors, and diabetes mellitus." (PMID 40704262, 2025). "This suggests that diabetes mellitus may lead to reduced serum AFP and PIVKA-II levels, potentially increasing the false-negative rate of AFP and PIVKA-II screening for HCC in T2DM patients." (PMID 39432605, 2024). "In our case, although the patient was older, other risk factors, such as male sex, fibrosis progression, diabetes, and elevated AFP levels, were not present." (PMID 39720368, 2024).
diabetes (continued). "Collectively, the present study confirmed the potential benefits of MT in downregulating the increased hepatic alpha-fetoprotein expression and in restoring pancreatic β-cells in a streptozotocin-induced diabetic rat model, suggesting its promising role in the treatment of diabetes." (PMID 37655263, 2023). "Patients who died were older, had a higher proportion of diabetes, tumor size ≥5 cm, AFP ≥ 400 ng/mL, higher total bilirubin (TBIL), γ-glutamyl transferase (GGT), creatinine (Cr), and international prothrombin ratio (INR), and lower albumin levels (allp < 0.001) than those who survived." (PMID 37215223, 2023). "However, after adjusting for sex and age, blood type was found to be correlated with polyp size, G-17, pepsinogen I (PGI), pepsinogen II (PGII), alpha-fetoprotein, which was almost consistent with the results after adjusting for sex, age, hypertension, diabetes, and coronary heart disease." (PMID 41578600, 2026). "Additionally, the absence of stratification and baseline differences in comorbidities, such as diabetes, tumor burden (size and number), AFP level, and BCLC stage, may further contribute to bias." (PMID 40647551, 2025). "Furthermore, the narrow range of gestational age at which AFP levels are markedly elevated and several other factors, including maternal diabetes or blood contamination of AF samples, may influence the results." (PMID 37048157, 2023). "The presence of diabetes mellitus (DM), multinodular disease, alpha-fetoprotein (AFP) over 300 ng/mL, and tumor dimension over 6 cm indicate poor overall survival." (PMID 35800821, 2022). "Moreover, consistent with published series, high serum AFP level and diabetes mellitus may strongly impact the outcome of HCC patients." (PMID 29555927, 2018). "In the RFS analysis, gender, diabetes, ALT, ALBI, AFP, APRI, ANRI, SIRI, MVI, number of tumours, tumour diameter, tumour capsule and PVTT were incorporated into univariate and multivariate Cox regression equations." (PMID 35255845, 2022). "The final model adjusted for age, sex, race/ethnicity, blood type, diabetes, obesity, laboratory MELD score, tumor size, AFP, locoregional therapies, UNOS region, and college education." (PMID 34945122, 2021). "Our multivariate competing risk analysis (adjusted for age, sex, race/ethnicity, blood type, diabetes, obesity, MELD score, tumor size in cm, AFP, UNOS region, locoregional therapies, and college education) included 2311 complete cases." (PMID 34945122, 2021). "For cases of cirrhosis, suspected advanced fibrosis according to NITs, and cases of diabetes mellitus, HCC should be surveyed by semi-annual US and measurements of tumor markers such as PIVKA-II, AFP, and AFP-L3." (PMID 32785100, 2020). "Univariate analysis identified that the following factors were significantly associated with the OS for patients with BCLC B-stage disease: diabetes; PT; APTT; serum levels of AST, ALT, ALB, TB, and AFP; and BMI." (PMID 32280472, 2020). "The evaluation identified 12 of the features as most important, including tumor size and number, surgical extent, lymph node metastasis, hepatitis B surface antigen (HBsAg), AFP, CA19-9, CEA, albumin, platelet count, diabetes mellitus, and cholelithiasis." (PMID 32140448, 2020). "When characteristics were compared of patients with HCC and those without, age, sex, the presence of diabetes mellitus (DM), T-Bil, Alb, PLT, AFP, FIB-4 index, aMAP risk and initial NA were significantly different." (PMID 35566481, 2022). "Patients with a higher level of post-treatment AFP within 1 year, and after 1 year, those with a history of more than two treatments for HCC or those with diabetes mellitus, which are related to post-treatment eGFR, require careful attention regarding the possibility of HCC recurrence." (PMID 34126947, 2021).
diabetes (continued). "Based on CSF levels of AFP and hCG, supervised PLS-DA and unsupervised cluster analysis showed that NGGCT patients are grouped apart from GGCT patients and subjects affected by other brain tumors or other diseases such as diabetes." (PMID 34829327, 2021). "Moreover, this study is the first to describe the influence of diabetes on the expression of hepatic markers (ALB, AFP), HNF-4α and miR-122 in NOD fetus liver." (PMID 28319104, 2017). "Then, the univariate Cox regression analysis included various factors, such as age, gender, drinking habits, diabetes, MASLD status, baseline ALT, HBV DNA, HBsAg levels, HBeAg status, HBV DNA decline at weeks 12 and 24, APRI score, total cholesterol, creatinine, glucose, AFP, and others." (PMID 40079003, 2025). "Serum AFP/PIVKA‐II levels were evaluated in 218 cirrhotics (163 males, 118 CTP‐A, 66 ALBI‐I, 111 with varices, 63 with diabetes) with (n = 90) or without (n = 128) HCC." (PMID 38361401, 2024). "In the RFS analysis, gender, diabetes, ALT, ALBI, AFP, APRI, ANRI, SIRI, MVI, no. of tumour, tumour diameter, tumour capsule, and PVTT were selected." (PMID 35255845, 2022). "Additionally, diabetes, small tumor size, non-HBV infection-related HCC, reduced TB, and glutamate transpeptidase (GGT) levels also influenced the AFP and PIVKA-II positivity rates in HCC patients." (PMID 39432605, 2024).
liver fibrosis (108 papers, 2008 to 2026). "The blood levels of secreted AFP can be used to accurately stratify patients with advanced liver fibrosis for their HCC risk and guide HCC screening." (PMID 38660138, 2024). "Specifically, we observed that age and AFP levels were associated with short-term improvement in liver fibrosis." (PMID 38808546, 2024). "In this study, we investigated the diagnostic value of serum AFP for liver fibrosis in HBeAg-positive CHB patients, as most CHB patients in China are HBeAg-positive." (PMID 37241155, 2023). "The blood-based PLSec-AFP sharply stratifies patients with advanced liver fibrosis who are at risk for long-term HCC and, therefore, gives a guide to risk-based, tailored HCC screening." (PMID 37627890, 2023). "Our results revealed that elevated serum AFP levels were not only associated with liver injury but also served as an independent predictor of liver fibrosis." (PMID 37241155, 2023). "Binary logistic regression analysis was performed to determine the independent associations between serum AFP levels and liver fibrosis." (PMID 37241155, 2023). "In recent decades, there have been numerous reports on the diagnostic value of serum AFP for liver fibrosis in patients with HCV infection." (PMID 37241155, 2023). "Advanced age, progression of hepatic fibrosis, male sex, and AFP level have been shown to be independent risk factors for hepatocellular carcinogenesis in hepatitis C patients." (PMID 35129720, 2022). "First, some important variables such as the AFP status, liver fibrosis score, health status, and underlying diseases had an excessive proportion of incomplete clinical information or were unavailable in the SEER database." (PMID 34336671, 2021). "Several recent reports have revealed that older age, male sex, advanced liver fibrosis, and high levels of α-fetoprotein (AFP) and alanine aminotransferase (ALT) are risk factors for developing HCC after achieving SVR." (PMID 29672518, 2018). "We found that a higher GGT level, lower platelet count, and higher APRI were associated with pretreatment AFP elevation and these factors are known to predict advanced hepatic fibrosis." (PMID 27335844, 2014). "Meanwhile, multiple factors such as advanced liver fibrosis, inflammation, and body composition were significantly associated with serum AFP." (PMID 23772356, 2013). "The severity of hepatic fibrosis was associated with the significant elevation of serum AFP level in our study." (PMID 23346149, 2012). "AFP levels have been shown to be associated with liver fibrosis." (PMID 38907187, 2024). "Additionally, when incorporating liver fibrosis, serum AFP, and the risk score into the survival analysis, only risk score was presented to be an independent prognostic indicator for HCC OS, while no significance of liver fibrosis and serum AFP was shown." (PMID 38374122, 2024). "Nonetheless, further studies are necessary to investigate whether serum AFP has similar diagnostic utility in evaluating HBeAg-positive CHB patients with varying degrees of liver fibrosis." (PMID 37241155, 2023). "PLT and AFP level were independently associated with LS, and their combination may improve the diagnostic performance and prediction of liver fibrosis." (PMID 33289529, 2021). "Since this treatment modality has been found to reduce AFP values, it may help to inhibit carcinogenesis in patients with elevated AFP values who are at high risk of cancer due to liver fibrosis." (PMID 26622488, 2015). "However, it is less clear whether serum AFP has similar diagnostic utility for liver fibrosis in CHB patients as compared to CHC patients." (PMID 37241155, 2023). "At present, surveillance decisions are currently based on the stage of liver fibrosis and consist on biannual ultrasound plus monitoring serum AFP levels." (PMID 40452835, 2025). "Ad-2D6 and CCl4-treated mice with histologically confirmed liver fibrosis presented with elevated blood AFP levels, whereas the Mdr2−/− mice had normal AFP levels." (PMID 38889481, 2024).
liver fibrosis (continued). "To examine if the iRGD-induced transport of AFP is detectable in mice with endogenously formed HCCs in the background of liver fibrosis, we examined the effect of iRGD in DEN-CCl4-treated mice with radiologically visualized HCCs." (PMID 38889481, 2024). "The interaction of AFP with CAFs is unclear, but AFP can promote HCC development in patients with liver fibrosis." (PMID 38660138, 2024). "Our findings showed positive associations between serum AFP levels and liver function parameters such as GLB, ALT, AST, and TBIL, which are components of non-invasive liver fibrosis scoring systems such as GP, FIB-4, APRI, and ALBI scores." (PMID 37241155, 2023). "The aim of the current study is to assess the accuracy of serum alpha-fetoprotein (AFP) in determining the stage of liver fibrosis in patients with chronic hepatitis B (CHB) who are positive for HBeAg." (PMID 37241155, 2023). "The FIB-4 index as a surrogate marker of liver fibrosis, serum albumin level, PT (%) as a marker of liver function, and the AFP level were measured at baseline, EOT, and SVR12 in all analyzed patients." (PMID 37268672, 2023). "In this study, we examined the efficacy of serum AFP in predicting liver fibrosis in HBeAg-positive CHB patients." (PMID 37241155, 2023). "HDCs transplantation also significantly reduced liver fibrosis by upregulating the expression of HGFs and lowering the serum levels of fibronectin and hepatic AFP." (PMID 35765490, 2022). "Significant differences were shown between the groups in terms of AFP level, platelet count, and Fib-4 index, which are indicators of hepatic fibrosis, at baseline." (PMID 35129720, 2022). "In conclusion, in Chinese outpatients with CHB, AFP outperforms ALT and/or AST in terms of their associations with LS, a useful tool for assessing liver fibrosis progression." (PMID 33289529, 2021). "Liver fibrosis markers, inflammatory indicator α-Fetoprotein (AFP), tumor necrosis factor-alpha (TNF-α), 25-hydroxyvitamin D, and PTH were estimated using immunoassay techniques." (PMID 33884041, 2021). "In particular, we found that the expression of CD11b+CD33+ MDSCs was positively correlated with AFP and hepatic fibrosis in patients with HCC." (PMID 33860040, 2021). "In that same study, sCD4 levels correlated with gamma-glutamyl transpeptidase, alkaline phosphatase, and alpha-fetoprotein, which the authors found to be suggestive of liver fibrosis." (PMID 34441792, 2021). "Further, the study aimed to provide a predictive tool for determining liver fibrosis degree based on AFP levels to help clinicians more effectively identify the risk of developing fibrosis in CHB patients." (PMID 33289529, 2021). "As expected, thrombocytopenia (PLT < 100 × 109/l) combined with a high AFP level (AFP > 8 ng/ml) also significantly increased prediction of liver fibrosis (OR = 11.216, 95% CI: 1.457–86.377, P=0.020)." (PMID 33289529, 2021). "The risk factors for HCC after achieving an SVR include age, gender, liver fibrosis stage, and alpha-fetoprotein (AFP) level." (PMID 31684167, 2019). "Previous studies have revealed that the risk factors for HCC after SVR were older age, male sex, advanced liver fibrosis, and high levels of AFP and ALT." (PMID 29672518, 2018). "The results indicate that the significant and independent risk factors for HCC development after SVR24 were age of ≥75 years, AFP levels of ≥6 ng/mL, and advanced liver fibrosis (SWE results of ≥11 kPa)." (PMID 29672518, 2018). "On the other hand, a univariate analysis of factors associated with advanced liver fibrosis among MICA A allele carriers included an older age, lower platelet counts, and higher AST, AFP and sMICA levels." (PMID 28427234, 2017). "The median values of AFP at liver fibrosis stages S0-1, S2, S3, and S4 were 3.0, 3.4, 5.4, and 11.3 ng/ml, respectively." (PMID 25128299, 2014).